TET1 (tet methylcytosine dioxygenase 1)
Diseases named in the same sentence as TET1 in open-access papers (continued):
Sharing a sentence is not in itself a finding about the gene and the disease.
tumor (continued). "Furthermore, functionally, ectopic expression of TET1 catalytic domain in cancer cell lines reactivated silenced tumor-suppressor genes (DLit2, ZNF382, HOXA9, and DKK1) and significantly suppressed clonogenicity of cancer cells compared to the catalytically dead mutant." (PMID 34209564, 2021). "Together with the findings that TET1 expression is increased in some BLBC, these data indicate that TET1 may play an oncogenic role in BLBC and such oncogenic role is partially associated with decreased inflammatory response and anti-tumor response." (PMID 34885145, 2021). "In addition, when crossing Tet1+/− mice with the SmoA1 mouse model, which has a high incidence of spontaneous MB development, we found a dramatic decrease in tumor incidence and tumor onset while the abolishment of Tet2 did not change tumor incidence and age-of-onset." (PMID 33926529, 2021). "Furthermore, we demonstrate that MAP7D1, regulated by TET1, promotes tumor growth and metastasis." (PMID 33716151, 2021). "Thus, TET1 may play a crucial role in regulating cholesterol and glucose metabolism in tumor cells, although the mechanisms need to be further explored." (PMID 34957093, 2021). "We also identify TET1 as a heretofore unknown MB oncogene and its role in tumor formation." (PMID 33926529, 2021). "In addition, the role of TET1 in tumours remains controversial." (PMID 34656178, 2021). "Taken together, these data suggest that TET1 may function as a tumor suppressor gene in UBC cells." (PMID 32528872, 2020). "To investigate the molecular mechanisms underlying reduced tumor cell proliferation upon TET1 KD in human T-ALL cells, we measured DNA (hydroxy)methylation and RNA expression changes, using MeDIP-, hMeDIP-, and RNA-seq analysis, comparing CCRF-CEM cells before (SCR) and upon TET1 KD (TET1sh)." (PMID 31266538, 2019). "Thus, TET1 may act as either tumor promotor or suppressor dependent on the context, a notion that also has been reported for other epigenetic regulators, including DNMTs." (PMID 31266538, 2019). "However, immunofluorescence staining results showed that the tumours from the fisetin‐treated group have significantly reduced Ki67 positive cell numbers, 5hmC oxygenase TET1 and biomarkers for tumour angiogenesis, CD31 and pVEGFR2 compared with the control group." (PMID 30411496, 2019). "DNA methylation profile of 24 tumour suppressors evidenced that SET accumulation decreased DNA methylation in association with loss of 5-methylcytidine, formation of 5-hydroxymethylcytosine and increased TET1 levels, indicating an active DNA demethylation mechanism." (PMID 28460463, 2017). "Interestingly, in our samples TET1 was downmodulated according to the tumor size." (PMID 28680536, 2017). "Thus, the anti-tumor effect of UC-514321 is also TET1-signaling dependent." (PMID 29235481, 2017). "Moreover, we reported previously that TET1 can recruit polycomb proteins to the promoter region of the mir-22 gene and suppress the primary transcription of this critical tumor-suppressor microRNA, and such transcriptional suppression is independent from TET1’s enzymatic activity." (PMID 29235481, 2017). "Laurent and colleagues also analyzed gene expression data from a cohort of breast cancer patients and revealed that both TET1 and TET2 expression significantly decreased with tumor progression (p < 0.0001)." (PMID 40116537, 2025). "Nevertheless, targeting the CLDN10B promoter with VP160 and TET1 in the dCas9 system not only demethylated and reactivated CLDN10B but also restored its tumor-suppressive function in a wound healing assay." (PMID 40524239, 2025). "In vivo, tumors derived from GATA6- or TET1-depleted CAFs exhibited reduced growth, proliferation, and CAF engraftment, underscoring their role in tumor progression." (PMID 40216762, 2025). "5hmC, TET1, TET2, and DNMT3B were primarily expressed in the nuclei of tumor cells, while SDHB exhibited granular cytoplasmic staining." (PMID 41290745, 2025).
tumor (continued). "This is consistent with other studies showing that both TET1 and TET2 expression leads to reduced tumor growth in xenograft mouse models." (PMID 40116537, 2025). "Overall, our findings demonstrate that GATA6 and TET1 are critical regulators of CAF identity, survival, and tumor-promoting functions." (PMID 40216762, 2025). "Epigenetic dysregulation in TALL involves MYC-mediated control of TET1/TET2 enzymes, where TET1 promotes oncogenesis via ribosomal biogenesis, while TET2 acts as a tumor suppressor." (PMID 40781676, 2025). "Our data revealed that CAFs with reduced GATA6/TET1 exhibited decreased secretion of IL-6, VEGF, and TGF-β (p < 0.05 vs. Control 1), critical mediators of angiogenesis and tumor-stroma crosstalk." (PMID 40216762, 2025). "Given TET1’s limited impact on CLDN10B induction and the elevated baseline expression in itspresence, we used dCas9-VP160 and demonstrate CLDN10B’s tumor-suppressive effects also in the 3D spheroid model." (PMID 40524239, 2025). "Targeting GATA6 or TET1 disrupted CAF identity, impaired tumor growth, and attenuated stromal-tumor crosstalk in vitro and in vivo." (PMID 40216762, 2025). "The expression levels of three writers (DNMT1, DNMT3A, DNMT3B), two erasers (TET1, TET3), and eight readers (MBD4, ZBTB33, UHRF1, UHRF2, UNG, TDG, NTHL1, SMUG1) were dramatically higher in tumor tissues (p < 0.05)." (PMID 38317133, 2024). "In addition to PD-1/PD-L1 expression and tumor mutational burden (TMB), several methylation regulators, such as ubiquitin-like with plant homeodomain (PHD) and ring finger domains 1 (UHRF1) and Ten-eleven translocation 1 (TET1), have been reported to be potential biomarkers for ICIs therapy." (PMID 38736884, 2024). "To investigate the tumor suppressive effect of RIPK3 after induction by epigenetic editing, we used VP160-dCas9 and TET1-dCas9." (PMID 38397165, 2024). "TET1 exerts an oncogenic role in AML as it upregulates the expression of oncogenes including HOXA9, MEIS1, and PBX3 and downregulates the tumor suppressor targets such as miR-22." (PMID 38696033, 2024). "We identified TET1, TET2, and TET3 as pivotal players influencing tumor progression, prognosis, immune response, tumor microenvironment, and drug sensitivity." (PMID 39104395, 2024). "TET1 inhibits cell invasion and adhesion in BT474 BC cells, as well as the cell proliferation and tumor growth through the re-expression of TIMP2 and TIMP3 genes via demethylation of their promoters in MDA-MB-231, MCF-7, and MDA-MB-468 BC cells." (PMID 38203443, 2023). "The results of Pearson correlation analysis showed that 5-hmC was negatively correlated with 5-mC and positively correlated with TET1 and IDH2 in tumor tissue." (PMID 37266610, 2023). "To investigate the expression of TET1 and TRPV4 in L4–6 DRG of BCP rats, we performed qPCR and Western blotting at days 0, 3, 7, 14, and 21 after tumor cell inoculation." (PMID 37190609, 2023). "There is also a positive correlation between TET1 and IDH2 in the tumor tissues of HBV-related HCC patients." (PMID 37266610, 2023). "TET1 re-expression induces Homeobox A9 (HOX9A) expression via demethylation of its promoter, decreasing cell invasion, tumor growth, and intravasation in MDA-MD-231 and MDA-MB-436 BC cells." (PMID 38203443, 2023). "In erasers, TET1 and TET3 were highly expressed in tumor tissues, while TET2 was down-regulated in tumor tissues." (PMID 37907576, 2023). "We also detected TET1 and IDH2 were decreased in the tumor tissues and the decrease were positively correlated with the 5-hmC." (PMID 37266610, 2023). "In this study, we showed that TET1 and TRPV4 expression was increased in L4–6 DRG after inoculation with Walker 256 tumor cells in rat tibia." (PMID 37190609, 2023). "Collectively, these data show that enforcing active TET2 CD expression mitigates the tumorigenicity of MCF-7 cells and are consistent with previous work showing that both TET1 and TET2 reduce tumor growth in xenograft mice." (PMID 35351824, 2022).
tumor (continued). "Although mutations of TET1 or TET3 are rarely detected in hematopoietic malignancies, in most TET2MT malignancies, TET1 and TET3 function as tumor repressors by compensating for TET2 activity." (PMID 36203205, 2022). "In HCC, TET1 and TET2 have been reported to be downregulated in tumor tissues and regulate DNA methylation." (PMID 35795047, 2022). "With the exceptions of TET1 and TET3, the expression levels of the other 11 factors were significantly different in the tumor tissues and the adjacent mucosal tissues." (PMID 35281843, 2022). "According to FIGO, TET1 and TET2 expression were lower than in neoplasms classified as stage I and II in more advanced tumors." (PMID 35409163, 2022). "Another study has shown that TET1 and TET2 enzymes have distinct functions in T-ALL development; TET1 acts as an oncogene in T-ALL, while TET2 is tumor suppressing." (PMID 33573325, 2021). "-miRNA-191 downregulated TET1 expression, an enzyme that is involved in the removal of methylated DNA in the loci of adenomatous polyposis coli (APC) and other tumor suppressor genes." (PMID 33800944, 2021). "We identified circMEMO1 as a crucial tumour suppressor in HCC metastasis and stemness that functions via the miR-106b-5p/TET1/5hmC/TCF21 axis and EMT process." (PMID 33985545, 2021). "In summary, we found that the expression profiles of TET1, 5-hmC, and 5-mC in ECs correlate with several factors, including tumor FIGO stage, tumor histological type, and nuclear grade." (PMID 34731191, 2021). "In addition, inhibition of Tet1 expression may contribute to tumor growth and angiogenesis in vivo." (PMID 35155564, 2021). "Herein, we found that TET1 expression was downregulated in UBC specimens compared with normal urothelium and was inversely related to tumor stage and grade and overall survival, suggesting its negative association with UBC progression." (PMID 32528872, 2020). "Here, we report that in T-ALL, the MYC oncogene controls the expression of both TET1 and TET2, which in turn contribute to tumor cell-specific 5mC and 5hmC patterns in a genome-wide fashion with importance for tumor maintenance." (PMID 31266538, 2019). "Since secretion of TFPI2 was also attenuated after TET1 KO, considering TFPI2 was a tumor suppressor of CRC and had been reported inhibited proliferation, we inferred H3R117A inhibited proliferation of LoVo cells by regulating TET1-mediated secretion of TFPI2." (PMID 30651599, 2019). "Afterward, in the same tumor tissues derived from RG‐QBC939 cells, expression of TET1 inversely correlated with P‐gp expression." (PMID 30784212, 2019). "To characterize the tumor immune microenvironment of TET1-MUT tumors, we compared the tumor immunogenicity and anti-tumor immunity between TET1-MUT and TET1-WT tumors." (PMID 31623662, 2019). "While the exact role of TET1 and TET2 in regulating DNA (hydroxy)methylation outside of developmental processes is not well understood, our findings indicate distinct functions of TET1 and TET2 in MYC-driven tumor maintenance." (PMID 31266538, 2019). "On the other hand, the tumor-infiltrating T lymphocytes, especially cytotoxic lymphocytes, were generally more abundant in the TET1-MUT tumors compared with those in the TET1-WT tumors across multiple cancer types." (PMID 31623662, 2019). "We generated methylation profiles of TET1, TET2 and TET3 genes in tumor samples obtained from 233 patients with HNSCC; these included 57 hypopharynx, 44 larynx, 69 oral cavity, and 63 oropharynx tumor samples." (PMID 29849955, 2018). "Induced levels of either TET1 or HOXA9 suppressed cell invasion in vitro and xenograph tumour growth and invasion when injected into nude mice mammary fat pads." (PMID 28587163, 2017).
tumor (continued). "Previous studies showed that TET1 can activate PARP-1/ARTD1 independently of DNA breaks and induce tumor cells apoptosis in multiple tissue types." (PMID 29156803, 2017). "Our study showed that 3,6-DHF effectively increases TET1 expression by inhibiting DNMT1 and DNA hypermethylation, and consequently up-regulates miR-34a in breast carcinogenesis." (PMID 28870206, 2017). "TET1 and TET2 generally act as tumor suppressors regulating cancer development, growth and invasion." (PMID 24939750, 2014). "Our results showed that level of TET1 protein was significantly decreased in HCC tissues, as compared with non-tumor tissues." (PMID 23671639, 2013). "We assessed the prognostic value of TET1 in BLCA using GEPIA, revealing that patients with high TET1 expression exhibited inferior survival, thereby providing additional evidence supporting its pro-tumor role in BLCA (Sfig." (PMID 40665298, 2025). "To obtain a more comprehensive insight into the epigenetic control of tumor aggressiveness, we performed an RT-qPCR analysis of the DNA methyltransferases DNMT1, 3A, and 3B, the DNA demethylases TET1, 2, 3, and TDG, and the RNA methyltransferase TRDMT1 in relation to tumor metastasis and invasion." (PMID 37367043, 2023). "Notably, after tumor cell inoculation, TRPV4 expression increased from day 7 while TET1 expression started to rise on day 3 only." (PMID 37190609, 2023). "We did not isolate enough tumor material to enable TET1 pulldown studies, which will be important to confirm our mechanism in future studies." (PMID 37231419, 2023). "However, TET1 and TET3 down-regulation sensitizes the breast tumor-initiating cells to paclitaxel and decreases the tumor growth and metastasis in vivo through down-regulation of the TNFα-p38-MAPK signaling pathway." (PMID 38203443, 2023). "Furthermore, the expression of TET1 and CRABP2 in tumor tissues of GC patients was positively correlated, as shown by qRT-PCR." (PMID 36195596, 2022). "Our results furthermore imply that C2C12 cells are de facto phenotypically Tet1 negative, while low overexpression levels correspond to the non-tumor human cell line MCF10a." (PMID 36056023, 2022). "Therefore, SMYD2 stimulated tumor growth and depressed cell senescence and apoptosis by regulating the EZH2/TET1 axis." (PMID 35668081, 2022). "In addition, tumor size and weight showed a more pronounced increase upon sh-TET1 + LLY-507 or sh-TET1 + AZ-505 than LLY-507 or AZ-505 alone, respectively." (PMID 35668081, 2022). "The expression of TET1 in BCa tumor tissues was downregulated compared with paired adjacent normal tissues." (PMID 35978806, 2022). "Analyses using paired samples indeed showed low levels of TET1 expression in tumor samples, and notably, further strong reductions in lymph nodes and distant organ metastases." (PMID 35805009, 2022). "Thus, it appears that the role of both TET1 and TET3 in hematological cancers (either oncogenic or tumor suppressive) is disease/context dependent and remains to be identified for MM." (PMID 36059621, 2022). "Due to the demethylation activity of TET1, its knockdown results in the up-regulation of ZEB2 expression as well as in up-modulation of the methylation level of the ZEB2 promoter, allowing promotion of malignant progression in tumor cells." (PMID 36140539, 2022). "The versatile functions of TETs may explain why changes in protein expression of TET1 and TET2 are more significant than changes in 5hmC in all the tumor specimens." (PMID 33716151, 2021). "Interestingly, transplantation of TET1-deficient cells isolated from the spleen or the lymph nodes of the TET1KO mice to congenic recipients could fully recapitulate the disease within 12 weeks, thereby establishing TET1 as a tumor suppressor of B-cell malignancy." (PMID 33520997, 2020). "We found that TET1 mRNA but not TET2 or TET3 was significantly reduced in tumor tissues compared with non-tumor tissues (P = 0.02, P = 0.55, and P = 0.21 respectively)." (PMID 31399111, 2019).
tumor (continued). "In contrast to TET1, our results show that TET2 acts as a tumor suppressor in T-ALL." (PMID 31266538, 2019). "We conclude that the MYC oncogene upregulates TET1 while suppressing TET2 expression in T-ALL, and speculated whether TET function was essential for tumor maintenance." (PMID 31266538, 2019). "Taken together, MICMIC along with MRA was able to identify causal events in tumorigenesis involving DNA methylation of distal regulatory regions, which we were able to verify via epigenetic editing by dCas9 fused with TET1 or DNMT3A-3 L and identify novel oncogenes/tumor-suppressors in the process." (PMID 29871649, 2018). "TET1 enzyme, along with TET2 and TET3, contributes to DNA demethylation through its conversion of 5mC to 5hmC and is considered to be a tumour suppressor, acting to prevent cell proliferation and tumour metastasis in human solid tumours." (PMID 28587163, 2017). "In contrast to the repression and tumor-suppressor role of TET2 observed in hematopoietic malignancies, we recently showed that TET1 was significantly upregulated in MLL-rearranged AML and played an essential oncogenic role in the development of MLL-fusion-induced leukemia." (PMID 29235481, 2017). "Furthermore, TET1 and TET3 expressions were decreased in tumor tissues from patients with intrahepatic tumor recurrence or extrahepatic metastasis compared with patients with no tumor recurrence (both P<0.05)." (PMID 28661477, 2017). "Clearly, the signals of 5mC, 5hmC and TET1 in tumor tissue were lower than those in the adjacent non-tumor tissue of the same patient." (PMID 27014907, 2016). "In one of the first studies reporting decreased levels of 5hmC in malignant tissue, it has been noted that the depleted 5hmC content did not correlate with the levels of Tet1/2/3 expression in a number of tumours." (PMID 26300993, 2015). "The expression of TET1 is decreased in HCC, which may have tumor suppressive effects." (PMID 38111040, 2023). "Considering the high expression of DNMT3A, TET1, DNMT3B, TET3, UHRF2, DNMT1, UHRF1and TDG in Subtype B, changing the tumor microenvironment cell infiltration characteristics by reversing expression of these DNA methylation regulators may be more clinically practical." (PMID 35771147, 2022). "Downregulation of TET1 was independent of tumor stage and the histopathological grade." (PMID 35269796, 2022). "Interestingly, we found that TET2 and TET3 were significantly higher in the tumor tissues compared with normal tissues, but not TET1." (PMID 29983831, 2018). "Moreover, TET1 expression was significantly higher in the early stage (tumor size < 10mm) neoplastic region than in the paired non-neoplastic region." (PMID 28680536, 2017). "Notably, the epigenetic modifiers TET1 (chromosome 10) and DNMT1/3B (chromosomes 19 and 20) were haploid and polyploid in tumour respectively, which suggests a connection between the observed hypermethylation (DNMT polyploidy) and 5hmC loss (diminished TET function) in the tumour." (PMID 29263824, 2017). "Because most cultured, immortalized tumor cells display reduced 5-hmC levels, we first investigated whether TET dioxygenases CDs actually were able to induce hydroxymethylation in A2780 cells by ectopic overexpression of untargeted TET1, -2 or -3." (PMID 24194590, 2014). "It is interesting that our MBD-seq and RRBS analysis revealed prominent methylation signatures in tumor cells only in the 3′-shore and not in CGIs or the 5′-shore, suggesting that TET1 transcription may be regulated by methylation in the 3′-shore but not CGIs or the 5′-shore in GCs." (PMID 26462176, 2015). "We previously reported significant elevation of pathway genes TET1, TARDBP, and SRSF2 in TNBC tumor samples obtained from obese (BMI > 30) compared to non-obese (BMI < 30) patients, as measured by qRT-PCR." (PMID 37231419, 2023). "The authors observed low TET1 and TET2 in tumors capable of metastasizing to regional lymph nodes compared to patients with non-dissipated neoplastic disease." (PMID 35409163, 2022).